BMI1 (BMI1 proto-oncogene, polycomb ring finger)
Diseases named in the same sentence as BMI1 in open-access papers (continued):
Sharing a sentence is not in itself a finding about the gene and the disease.
tumor (continued). "Throughout the experiment, real-time RT-PCR analysis and immunohistochemical (IHC) analysis of the pathologic sections of these tumors showed that SB-treated tumor had increased miR-494 expression and decreased Bmi1 and ADAM10 expression in comparison to those from control HNC-TICs tumors." (PMID 26090866, 2015). "Furthermore, inverse correlation between miR-200c level and expression of BMI-1, as well as tumor progression, is evidenced in our clinical relevance study." (PMID 25367080, 2014). "Overexpression of Bmi-1 may reduce the expression of p16 and p19Arf, which induce anti-senescence in tumor cells." (PMID 25364434, 2014). "Bmi-1 exerts it effects by suppression of the p16Ink4A/ARF tumor suppressor." (PMID 25051360, 2014). "Sphere formation in serum-free suspension cultures has been well established as a means to enrich for cells with CSC-like properties, including drug resistance, self-renewal capability, high expression of stem cell markers (e.g., CD44, ALDH and BMI1), tumor initiation, and differentiation capacity." (PMID 25471937, 2014). "In addition, Bmi-1 can induce the coordination of the c-myc gene with p16 to promote cell transformation and tumor formation, which results in the cell escaping apoptosis." (PMID 25364434, 2014). "Bmi-1 has been proposed to be an oncogene that can induce anti-senescence in tumor cells." (PMID 25364434, 2014). "To further estimate the relative abundance of BMI1 positive tumor cells, we performed IHC staining." (PMID 25526772, 2014). "Indeed, the high level of Bmi-1 in Prep1i/i leukemic cells correlates with a significant reduction of the p16Ink4a and p19Arf tumor suppressors." (PMID 24809472, 2014). "Importantly, Bmi1 knockdown can block the tumor growth, both in the initiating stages and the fast growing stages." (PMID 25372945, 2014). "Similarly, PcG group proteins have been implicated in human carcinogenesis and some, including BMI1 and EZH2 are bona fide oncogenes that are overexpressed in many tumor types." (PMID 23673719, 2013). "Moreover, spheroid-selected A431 cells express increased levels of stem cell markers, including Bmi-1, Sox2, Ezh2 and H3K27me3, and spheroid-selected A431 cells are highly efficient tumor forming cells." (PMID 24376802, 2013). "In the present study, we observed expression changes and epigenetic modulations of several key tumor-related genes, including tumor suppressor genes, p21WAF1 (p21) and p16INK4a (p16), and tumor promoting genes, BMI1 and c-MYC, during early breast tumorigenesis in vitro and in vivo." (PMID 23342141, 2013). "Over-expression of BMI1 was correlated with tumor clinic-pathological features." (PMID 23820733, 2013). "Moreover, a trend to larger tumor size was seen in the tumors formed by Bmi1 expressing cells compared to control MiaPaCa2 cells (0.27±0.17 cm3 vs. 0.98±0.41 cm3, p = NS)." (PMID 23437065, 2013). "However, mice implanted with BMI1-overexpressing tumors reached the preset end-point tumor volume at 35th day of post-implantation." (PMID 23671559, 2013). "This would be the first report showing BMI1 as a secretory protein from tumor cells." (PMID 23308129, 2013). "However at this point, BMI1-silenced group treated with docetaxel exhibited only an average tumor volume of 230 mm3 suggesting that knocking down of BMI1 sensitized tumor cells to therapy." (PMID 23671559, 2013). "An increased expression of p16, p15 and TIMP3 in BMI1-silenced tumor cells was observed." (PMID 23671559, 2013). "The data suggested a possible association between the BMI1, BCL2 and Cyclin-D1 in tumor cells." (PMID 23671559, 2013). "Furthermore, GE treatment increased expression of two crucial tumor suppressor genes, p21WAF1 (p21) and p16INK4a (p16), although it decreased expression of two tumor promoting genes, BMI1 and c-MYC." (PMID 23342141, 2013).
tumor (continued). "The involvement of FAK in regulating BMI-1 expression does not exclude other contributions of this kinase to the function of TICs, although its ability to induce GLI1 and, consequently, BMI-1, provides an important mechanism for its involvement in tumour formation." (PMID 23436775, 2013). "In addition to larger tumor size, Bmi1 expressing cells displayed enhanced metastatic potential in vivo." (PMID 23437065, 2013). "However, BMI1-overexpressing tumors though treated with docetaxel reached an average tumor volume of 997 mm3 at 35th day." (PMID 23671559, 2013). "Since both TCF and BCL2 were observed to be under the guidance of BMI1, we next investigated whether there is a direct association of TCF and BCL2 gene in tumor cells." (PMID 23671559, 2013). "In addition, overexpression of Bmi-1 increases tumour formation, ionizing radiation resistance, local invasion, distant metastasis to the lungs, and tumour size in vivo." (PMID 23533441, 2013). "We next identified the expression of BMI1 in human CaP specimens by immunohistochemical analysis and determined its expression levels in stromal regions of 70 pair-matched specimens of normal and CaP representing all tumor stages." (PMID 23308129, 2013). "The control of tumor suppressor loci by chromatin regulatory complexes, such as those containing Bmi1, may be a strong determinant of responses to oncogenic signaling." (PMID 22654667, 2012). "Patients harbouring BMI1-positive tumour cells showed significantly poorer prognoses than those without such cells or residual tumours (mean disease-free survival (DFS) time 16.8 vs 71.2 months; 3-yr DFS 13.3% vs 49.9%, P=0.002; mean OS time 21.8 vs 76.6 months; 3-yr OS 16.2% vs 54.9%, P=0.0005)." (PMID 23046527, 2012). "Thus, the results underscore the importance of Bmi-1 targeting in combination with irradiation in tumor therapy." (PMID 22209830, 2012). "Thus, Bmi1 expression is required for tumor cell proliferation during AKT/Ras induced hepatocarcinogenesis." (PMID 23029524, 2012). "Therefore, it is assumed that the proto-oncogene Bmi1 positively contributes to tumor formation in these cases." (PMID 22574128, 2012). "The incomplete penetrance and long latency period (1 year) of tumor formation upon Bmi1 over expression suggested that additional genetic or epigenetic defects might facilitate the generation of tumors." (PMID 22574128, 2012). "We hypothesized that Bmi-1 inhibition combined radiotherapy could induce synergistic effect on MCF-7 tumor cells." (PMID 22209830, 2012). "Overexpression of Bmi-1 enhanced in vivo tumor growth in HNSCC-ALDH1−." (PMID 20936121, 2011). "Bmi-1 has also been reported to be involved in tumor metastasis." (PMID 20936121, 2011). "We next sought to determine if Bmi-1 expression could modulate the in vivo tumor initiating activity in immunocompromised nude mice." (PMID 20936121, 2011). "Moreover, overexpression of Bmi-1 inHNSCC-ALDH1− cells increased tumor volume and number of pulmonary metastatic lesions by xenotransplantassay." (PMID 20936121, 2011). "Furthermore, tumor volumes in HNSCC-ALDH1+ transplanted mice were significantly decreased when mice were treated with sh-Bmi-1." (PMID 20936121, 2011). "It is possible that the power of massive lymphocytes closely contacting with invasive tumor cells, may augment the immunoreactive to Bmi-1 antigen, which facilitates the production of Bmi-1 antibodies." (PMID 20809956, 2010). "These tumour spheroid cells retain the expression of well-known cell surface markers, including CD133, CD166, CD44, and EpCAM, as well as other stem cell-associated proteins such as NES, BMI-1, and MSI-1." (PMID 20332776, 2010). "A reason for this may be the observed large variation in tumor Bmi-1 levels in both materials and tumor heterogeneity may be responsible for the observed differences." (PMID 21162745, 2010). "Bmi-1 has been shown to be up-regulated in breast tumors as well as in several other tumor types." (PMID 21162745, 2010).
tumor (continued). "The highest transcription level of Bmi-1 was observed in invasive tumor tissue." (PMID 21162745, 2010). "Expression of bmi-1 and ngx6 can therefore serves as an indicator for tumour development." (PMID 20964870, 2010). "However, correlations were significant between anti-Bmi-1 and tumor stage (P = 0.040), and lymph node status (N classification; P < 0.001)." (PMID 20809956, 2010). "In these reports, Bmi-1 protein mainly locates in nuclei of tumor cells." (PMID 20809956, 2010). "Case 4 and case 8 contained high amounts of tumor cells with high levels of Bmi-1 expression." (PMID 20809956, 2010). "It suggests that Bmi-1 protein may play a role in tumor metastasis, especially in lymph node metastasis." (PMID 20809956, 2010). "In addition, Bmi-1 expression was observed in 64.3% (110 of 171) archive ESCC specimen by immunohistochemistry analysis, and the location of Bmi-1 in ESCC was in the nuclei instead of cytoplasm of tumor cells." (PMID 20809956, 2010). "Here we examine whether tumor initiation and growth requires the stem cell self-renewal factor Bmi1." (PMID 19156217, 2009). "Further, to determine whether expression of Bmi1 is correlated with tumorigenicity in vivo, we performed a histological examination that detected Bmi1 in the mouse tumor xenografts." (PMID 19917110, 2009). "Ablation of Bmi1 expression in both lines had a dramatically decreased tumor growth." (PMID 19156217, 2009). "Interestingly, Mel-18 behaves as a tumor suppressor by repressing oncogenes Bmi-1 and c-myc in mammals." (PMID 19333393, 2009). "In summary the ablation of Bmi1 in BXB11 mice leads to strongly reduced tumor growth." (PMID 19156217, 2009). "In contrast no significant reduction in tumor initiating events could be observed in both founder lines, arguing for Bmi1 being an important factor for tumor expansion rather then initiation." (PMID 19156217, 2009). "Conversely, BMI1 expression is negatively correlated (-0.27) with tumour cell proliferation." (PMID 19099573, 2008). "However, overexpression of BMI1 can keep the tumour suppressive INK4a/ARF locus silenced, even in the presence of oncogenic signaling, providing an explanation for the collaboration between BMI1 and c-Myc in tumourigenesis." (PMID 19099573, 2008). "The differential association with survival suggests that EZH2 and BMI1 are not overexpressed in the same tumours." (PMID 19099573, 2008). "In addition, we found that high BMI1 levels are mainly restricted to ER-positive luminal A type tumours." (PMID 19099573, 2008). "In tumour-free, normal lung tissue from patients, weak – moderate bmi-1 staining was seen in some epithelial cells, lymphocytes, glandular cells and in fibroblasts, whereas blood, endothelial, chondrocytes, muscle cells and adipocytes did not exhibit any bmi-1 expression." (PMID 11355949, 2001). "BMI1 induces the ubiquitination of histone H2A, which suppresses the expression of zinc finger protein 24 and decreases the secretion of vascular endothelial growth factor A, thereby promoting tumor angiogenesis and providing support for tumor cell proliferation and metastasis." (PMID 41268614, 2026). "For example, Bmi‐1 affects the expression of genes involved in cholesterol production and transport as well as alternative splicing events related to cholesterol metabolism, thereby modulating cellular lipid homeostasis and metabolic processes critical for tumor growth and survival." (PMID 39791545, 2025). "Given that Cdkn2c is a known tumor-suppressor gene that regulates cell proliferation, the decreased proliferation observed in inner ear progenitor cells following Bmi1 knockout might be attributed to the increased expression of p18INK4c due to the decrease in H3K27me3 levels." (PMID 41257804, 2025). "Therefore, we used fluorescently labeled H1299 cells to establish an orthotopic model in BALB/c mice to study whether BMI1 inhibitors can further enhance the anti-tumor effect of Bevacizumab." (PMID 39349443, 2024).
tumor (continued). "Overall, these data show that BMI-1 knockdown in H1975 cells affects tumorigenesis similarly to Unesbulin-mediated and PTC-028–mediated effects, supporting the hypothesis that BMI-1 pharmacologic inhibition achieved through these novel compounds inhibits tumor growth in a BMI-1–dependent manner." (PMID 38546390, 2024). "Our results indicated that BMI1 overexpression increased cell growth, colony formation, cell migration and cell invasion as well as tumor sphere formation in WBBMI1 and PLCBMI1 cells compared to control cells (i.e., empty vector transfected cells, WBCtrl/PLCCtrl cells)." (PMID 37923799, 2023). "Indeed, miR-15/16 are known tumor suppressors, best characterized in B cell leukemia, which affect cell growth by restricting cell-cycle and anti-apoptotic genes such as Ccnd1 (cyclin D1), Bmi1, Bcl2, and Mcl1." (PMID 37862171, 2023). "The difference in significance between our results and the results of the other studies may be related to the difference in tissue type, where we used bone marrow samples to detect BMI1 expression while the other studies used tumour tissue biopsies to detect this marker." (PMID 36966176, 2023). "Importantly, SNHG3/c‐MYC/BMI1 axis may be a novel target for regulating tumor growth and metastasis in BLCa patients." (PMID 36208024, 2023). "In CSCs, overexpression of the transcription factor Nanog, in coordination with Oct-4, Sox-2, Bmi-1 and other complexes, enhanced the characteristic expression of CSCs and activated their self-renewal, metastasis, invasion, angiogenesis and drug resistance, thereby reducing tumor cell apoptosis." (PMID 38095348, 2023). "We then tested whether BMI1 regulates the tumour initiation activity of LAC cells." (PMID 35794816, 2022). "Furthermore, PTC-209 treatment significantly inhibits proliferation and promotes apoptosis in multiple myeloma (MM) cells, suggesting that BMI-1 may serve as an attractive anti-tumor drug target." (PMID 36076977, 2022). "Therefore, the role of Bmi-1 in the tumor microenvironment needs to be further explored." (PMID 35897796, 2022). "Interestingly, others have shown that Bmi-1+ cells represent a subset of CSCs that might be responsible for therapeutic resistance and tumor recurrence." (PMID 34689150, 2021). "Interestingly, concomitant downregulation of the Bmi-1 oncogene and upregulation of p-AMPKα would suggest that suppression of Bmi-1 underlies BA-mediated, AMPK-mTOR-ULK1-dependent, activation of autophagy and apoptosis in tumor cells." (PMID 34510030, 2021). "Furthermore, the Bmi-1/miR-27a/RKIP and Bmi-1/miR-155/RKIP signaling axes might be potent targets for novel therapeutic approaches against human GC due to their demonstrated roles in tumor metastasis and drug resistance." (PMID 32580736, 2020). "Hence, it has been hypothesized that Bmi-1 could contribute to tumor metastasis by increasing MMP-2, MMP-9, and VEGF expression through the PTEN/PI3K/Akt pathway." (PMID 31466358, 2019). "Also, UA as an enhancement factor might also have induced tumor cell apoptosis, making the potential apoptosis promotion by Bmi1 siRNA less evident." (PMID 31366257, 2019). "Although it is well known that BMI-1 has an important role in the modulation of self-renewal and cell differentiation potential of hematopoietic stem cells (HSCs) and neuronal stem cells (NSCs), BMI-1 is also a key regulator of the self-renewal, differentiation and tumor initiation of CSCs." (PMID 31382410, 2019). "Thus we examined whether the NT1721-mediated reduction of BMI1 expression induced the re-expression of these tumor suppressors." (PMID 31661013, 2019).
tumor (continued). "In addition, in vivo experiments revealed that 1) tumor formation rate of subcutaneous inoculation reduced from 100% to 50% after BMI1 silencing and 2) the average xenografted tumor size was dramatically smaller in the BMI1 knock-out group (5.3 mm3) than in the wild-type group (1986.7 mm3)." (PMID 29685168, 2018). "Results of these experiments documented significant inhibition of the Bmi1 mRNA and protein expression in CSCs and showed that inhibition of Bmi1 expression in these cells abrogates stem cell-specific properties and significantly reduces tumor growth in animals." (PMID 28418883, 2017). "Results from hierarchy clustering and linear regression analyses showed that the expression of tumor-associated ASC and IL-18 are closer to ALDH1 expression, NLRP3 and Caspase-1 are close to ALDH1 expression, and NLRP3, Caspase-1, ASC, and IL-18 are close to CD44 and BMI1 expression." (PMID 28865486, 2017). "In addition, BMI-1 is involved in tumor growth and is required for CSC renewal and differentiation." (PMID 29299167, 2017). "In addition, our western blot results showed that NLRP3, Caspase-1, IL-18 and IL-1β were highly expressed in the Tgfbr1/Pten 2cKO mice SCCHN tumor lysates compared with control wild type tongues, and the expression of BMI1, ALDH1 and CD44 were consistent with NLRP3 inflammasome." (PMID 28865486, 2017). "Our results revealed a mechanism of methylation that controls miR128-1 expression in GBM cells and GSCs and indicate miR128-1 could function as a tumor suppressor in GBM by negatively regulating tumor cell proliferation, invasion and self-renewal through direct targeting BMI1 and E2F3." (PMID 27705931, 2016). "Thus, a transient Bmi1 expression as it occurs in ADM cells might be solely achieved through a loss of H2AK119ub, whereas a persistent expression in tumor cells might be additionally guaranteed by reduced H3K27me3 levels." (PMID 26716510, 2016). "Our results suggest CSCs are present in both, tumors and blood of NSCLC patients, whereas Bmi1 may play an important role in initiation and maintenance of stemness properties of tumor cells of NSCLC patients and might be involved in blood-borne dissemination of NSCLC tumors." (PMID 26770215, 2016). "Our observation of increased BMI-1 expression in relapsed TT3 patients suggests that further BMI-1 upregulation might confer a more aggressive phenotype during the progression of MM as it was shown in the progression of several other tumour entities." (PMID 26935956, 2016). "Thus, we investigated if knockdown of Bmi1 had any effect on tumor initiation in xenograft models." (PMID 25348805, 2014). "To further investigate whether this upregulation of p16INK4a was reflecting changes in the transcription levels of known regulators of this tumor suppressor, such as Bmi1 15,25, Ezh1 26, Ezh2 27,28, and Suz12 29, we analyzed the expression of these genes by qPCR." (PMID 24307508, 2014). "To test our hypothesis we asked if BMI1 is secreted by tumor cells under culture conditions." (PMID 23308129, 2013). "Our further results showed that GE treatment induced a differential expressional pattern of several tumor-related genes, including increased expression of two crucial tumor suppressor genes, p21 and p16, and decreased expression of two tumor promoting genes, BMI1 and c-MYC." (PMID 23342141, 2013). "In addition, Bmi1 has been shown to function as an oncogene in multiple tumor types." (PMID 23029524, 2012). "Thus in reference to EWS-FLI1, disparate molecular mechanisms may contribute to BMI-1's function as an oncogene during tumor initiation and tumor maintenance and we hypothesize that BMI-1 targets change and evolve during ESFT initiation and progression." (PMID 21559395, 2011). "Moreover, the location of Bmi-1 in ESCC was in the nuclei instead of cytoplasm of tumor cells." (PMID 20809956, 2010). "The absence of Bmi-1 protein in the tumour cells was associated with a higher risk of recurrence." (PMID 20145620, 2010).